ANGPTL2 (angiopoietin like 2)
Diseases named in the same sentence as ANGPTL2 in open-access papers (continued):
Sharing a sentence is not in itself a finding about the gene and the disease.
tumor (continued). "We also reported that stroma-derived ANGPTL2 contributes to tumor suppression via macrophage-mediated CD4+ Th1 cell anti-tumor responses." (PMID 37736764, 2023). "Here, we report that tumor cell‐derived ANGPTL2 contributes to tumor progression by accelerating epigenetic repression of MHC‐I expression in tumor cells, resulting in their evasion of CD8+ T‐cell‐mediated anti‐tumor immune responses." (PMID 37452654, 2023). "Accordingly, here, we demonstrate that tumor cell‐derived ANGPTL2 contributes to tumor cell evasion of CD8+ T‐cell‐mediated anti‐tumor immunity by suppressing MHC‐I expression." (PMID 37452654, 2023). "Together with our previous study, these results suggest that tumor cell‐derived ANGPTL2 accelerates tumor progression in tRCC pathology." (PMID 37452654, 2023). "A recent study has revealed that miR-378a-3p enhances osteolysis and then promotes release of ANGPTL2, which leads to tumor progression." (PMID 37426414, 2023). "Further studies are needed to define ANGPTL2‐mediated transcriptional regulatory mechanisms of JARID2 in tumor cells." (PMID 37452654, 2023). "Mechanistically, we show that in tumor cells the ANGPTL2‐α5β1 integrin pathway promotes PRC2‐mediated H3K27me3 deposition at promoters of antigen presentation‐related genes, including MHC‐I, via JARID2 induction." (PMID 37452654, 2023). "More recently, we showed that tumor stroma-derived ANGPTL2 enhances dendritic cell (DCs)-mediated CD8+ T cell anti-tumor immune responses." (PMID 37736764, 2023). "Mechanistically, we found that CAF-derived ANGPTL2 activates DCs and macrophages in a paracrine manner, facilitating anti-tumor immune responses by T cells." (PMID 37736764, 2023). "A recent study discovered that host ANGPTL2 also shows tumor-suppressive activity by enhancing dendritic cell-mediated CD8+ T-cell antitumor immune responses in murine syngeneic models." (PMID 35719407, 2022). "Angptl2 contributes to the inflammatory environment that facilitates carcinogenesis and metastasis by promoting epithelial-to-mesenchymal transition, tumor migration, tumor angiogenesis, and lymph-angiogenesis." (PMID 34830112, 2021). "Tumor cell-derived angiopoietin-like protein 2 (ANGPTL2) activates tumor cell motility, invasiveness, and epithelial-mesenchymal transition to accelerate tumor metastasis in an autocrine/paracrine manner." (PMID 34007851, 2021). "According to our functional analysis of co‐expressed genes in GC, ANGPTL2 probably participate in the development of tumor microenvironment, especially vasculature development." (PMID 32410376, 2020). "The absolute number of neutrophils in the lung were significantly lower in ANGPTL2 depleted tumor cells verifying essential role of tumor secreted ANGPTL2 in neutrophils recruitment." (PMID 32082485, 2020). "We determined that tumor-derived ANGPTL2 stimulates lung epithelial cells, which is essential for primary tumor-induced neutrophil recruitment in lung and subsequent pre-metastatic niche formation." (PMID 32082485, 2020). "In contrast, serum ANGPTL2 levels were dramatically lower in mice bearing ANGPTL2-suppressed tumor cells." (PMID 32082485, 2020). "ANGPTL2 also increased cancer cells’ migratory and invasive ability, thus facilitate tumor metastases through different mechanisms." (PMID 32410376, 2020). "ANGPTL2 mainly exerted its pro‐angiogenic and antiapoptotic abilities in the tumor microenvironment." (PMID 32410376, 2020). "Angiopoietin-like protein 2 (ANGPTL2) is a secretory glycoprotein involved in vascular biology, inflammation, and tumor development." (PMID 32923383, 2020). "ANGPTL2 Knockdown with small interfering RNA decreased cellular proliferation and inhibited tumor cell migration." (PMID 31384179, 2019). "We found ANGPTL2 mRNA level was positively correlated with the T stage, which reflected the tumor size and invasion." (PMID 31384179, 2019). "The ratio of the cases with ANGPTL2 mRNA level high expression was increased along with the development of PTC tumor." (PMID 31384179, 2019).
tumor (continued). "Several research evidences have showed that ANGPTL2 was upregulated in various human tumor tissues and correlated with tumor size and severity." (PMID 31384179, 2019). "The effect of ANGPTL2 in induction of tumor cell metastasis via different protein in different type of cancer have been reported, such as integrin α5β1, p38 mitogen activated protein kinase (MAPK), and matrix metalloproteinase (MMP)-9." (PMID 31384179, 2019). "The mRNA Level of ANGPTL2 increased with cancer severity stage and positively correlated with tumor volume." (PMID 31384179, 2019). "In fact, elevate levels of ANGPTL2 in EC tissues correlate with a higher tumour, node and metastasis (TNM) staging classification stage in patients affected by esophageal tumor." (PMID 29389861, 2018). "Up to date several studies reported the role of ANGPTL2 in cancer suggesting it as a tumor promoting gene." (PMID 29389861, 2018). "In cancer cells, ANGPTL2 promotes epithelial to mesenchymal transition, a critical step for tumour invasive properties and metastasis, via activation of the TGFβ-Smad pathway." (PMID 29138671, 2017). "In the context of cancer, ANGPTL2-induced inflammation creates a deleterious environment that favours genomic instability and DNA damage and thus contributes to all stages of tumour development, from initiation to progression." (PMID 29138671, 2017). "In these conditions, ANGPTL2 expression increases in infiltrating immune cells or resident cells, such as adipocytes, vascular endothelial cells and tumour cells." (PMID 27677409, 2016). "Such graded methylation has been previously reported in cancer: methylation of ANGPTL2 varies proportionally with tumour metastasis." (PMID 27101308, 2016). "Patients were divided into two groups based on percentage of ANGPTL2-positive tumor cells at the primary tumor site: the positive group was defined as showing ≥50% ANGPTL2-positive tumor cells, while the negative group showed <50%." (PMID 25773070, 2015). "Integrin α5β1, which acts as functional receptor for ANGPTL2 in endothelial cells and monocytes/macrophages, is also expressed in several cancer cells, in which it regulates tumor cell growth and invasion." (PMID 25370833, 2015). "Our findings also suggest that ANGPTL2 increases bone metastasis by up-regulating CXCR4 in primary tumor cells, thereby enhancing their responsiveness to bone tissue-secreted CXCL12." (PMID 25773070, 2015). "To understand the mechanism by which ANGPTL2/LILRB2 controls tumor growth, we analyzed apoptosis and the cell cycle status of A549 cells knockdowned with shRNA targeting LILRB2 or with a control shRNA." (PMID 26056041, 2015). "Other factors that are secreted by the primary tumor, such as G-CSF, angiopoietin-like protein 2 (ANGPTL2), IL-6, and CCL2, promote the expansion of the myeloid lineage, their recruitment into the lung PMN and their polarization into an immunosuppressive phenotype." (PMID 40370456, 2025). "Given the complexity of the tumor microenvironment and the fact that both tumor‐intrinsic and microenvironmental activities regulate anti‐tumor immunity, it may be challenging to correlate ANGPTL2 mRNA levels with those of CD8A." (PMID 37452654, 2023). "We found higher levels of ANGPTL2 mRNA expression in tumor tissue than in adjacent normal tissue." (PMID 36917086, 2023). "Further studies are needed to determine whether ANGPTL2 signaling in tumor cells contributes to acquisition of resistance to ICI therapy in both tRCC and ccRCC." (PMID 37452654, 2023). "Our present study suggests that an ANGPTL2–chemokine axis in CAFs may attract T cells to tumor tissues and function in tumor suppression, although further studies are needed to confirm this possibility." (PMID 37736764, 2023). "Moreover, we provide evidence that the ANGPTL2‐α5β1 integrin pathway accelerates polycomb repressive complex 2‐mediated repression of MHC‐I expression in tumor cells." (PMID 37452654, 2023).
tumor (continued). "Next, we asked how tumor cell‐derived ANGPTL2 promotes tRCC progression." (PMID 37452654, 2023). "In addition, we previously showed that ANGPTL2–integrin α5β1 signaling in tumor cells has tumor-promoting activity." (PMID 37736764, 2023). "By contrast, tumor cell‐derived ANGPTL2 accelerated tumor progression." (PMID 37452654, 2023). "Overexpression of ANGPTL2 in CL1-0 cells increased tumor growth." (PMID 36917086, 2023). "The ANGPTL2–α5β1‐integrin pathway in tumor cells accelerates polycomb repressive complex 2‐mediated repressive histone modification at the major histocompatibility complex class I (MHC‐I) promoter via JARID2 induction, thereby attenuating interferon γ‐induced MHC‐I expression in tumor cells." (PMID 37452654, 2023). "In contrast, ANGPTL2 blockade suppressed tumor growth and the levels of ANGPTL2, LYVE-1 and VEGF-A." (PMID 36917086, 2023). "Studies have shown that ANGPTL2 is highly expressed in tumor tissues and has a procancer effect." (PMID 35692877, 2022). "ANGPTL2 has been proved to be tumor‐promoting among several types of cancer." (PMID 32410376, 2020). "Collectively, by using spontaneous metastatic models, we investigated whether tumor secreted ANGPTL2 induces inflammation on lung epithelial cells by activating alpha5beta1 (α5β1) receptor and recruiting neutrophils to the pre-metastatic niche." (PMID 32082485, 2020). "Taken together, our results suggest that activation of lung epithelial α5β1 receptor by ANGPTL2 induces chemokine production that effect neutrophil recruitment in ways that create a tumor-growth-favoring lung microenvironment for disseminated metastatic cancer cells." (PMID 32082485, 2020). "Next, we checked the ANGPTL2 protein level in PTC tissue with different tumor size." (PMID 31384179, 2019). "Results showed that ANGPTL2 protein was positively correlated with PTC tumor volume." (PMID 31384179, 2019). "The correlation between ANGPTL2 protein level and tumor size was evaluated." (PMID 31384179, 2019). "The result showed that ANGPTL2 levels were increased in the advanced stage of PTC tumor." (PMID 31384179, 2019). "We report de‐repression of Bmp2 and Bmp7 in Angptl2−/− ISEMFs and decreased accumulation of β‐catenin in Angptl2−/− mouse crypts, suggesting that ANGPTL2 may function as a tumor promotor in intestine." (PMID 28043948, 2017). "It has been proposed that ANGPTL2 secreted from cancer cells activates the integrin α5β1/Rac1 pathway, promoting both autocrine and paracrine effects, increasing tumour cell invasion, motility, tumour angiogenesis, and thus tumour metastasis." (PMID 29138671, 2017). "Similarly, the same team proposed that elevated ANGPTL2 circulating levels measured in gastric cancer patients are likely produced by the tumour and the adjacent normal mucosa." (PMID 29138671, 2017). "Angptl2 is a mediator chronic inflammation, increased oxidative stress and tumor progression." (PMID 27270319, 2016). "To investigate whether tumor cell-derived ANGPTL2 enhances the ability of cells to colonize a metastatic site, we injected MB231/miANGPTL2/luc or MB231/miLacZ/luc cells into the left cardiac ventricle of immunodeficient mice and assessed metastasis." (PMID 25773070, 2015). "Furthermore, ANGPTL2 expression in lung tumor cells is highly correlated with the frequency of tumor cell metastasis through increased tumor angiogenesis." (PMID 25370833, 2015). "We have reported that calcineurin/NFAT pathways could induce Angptl2 expression in tumor cells, and hypoxia-increased Angptl2 expression was suppressed by calcineurin inhibition in a human keratinocyte cell line, HaCaT." (PMID 24465594, 2014). "On the contrary, in our experimental set up WA decreased EMT-related components of the TGF-β signaling pathway (TGFA, TGFBR2, CDH11), as well as TGM2, HIF1A, several TNFSF family members and ANGPTL2, which stimulate tumor promoting pro-inflammatory responses and a hypoxic microenvironment." (PMID 24498382, 2014).
tumor (continued). "A possible explanation for these contradictory effects is that ANGPTL2 plays distinct roles depending on its source: tumor cell‐derived ANGPTL2 promotes tumor progression, whereas stromal cell‐derived ANGPTL2 may have tumor‐suppressive effects (Horiguchi, Kadomatsu, and Oike 2024)." (PMID 41508557, 2026). "However, mechanisms underlying ANGPTL2-mediated tumor suppression are complex and not yet fully understood." (PMID 37736764, 2023). "However, it remains unclear how the ANGPTL2‐α5β1 integrin pathway regulates JARID2 expression in tumor cells." (PMID 37452654, 2023). "Importantly, overexpression ANGPTL2 facilitated tumor growth and lymphangiogenesis in vivo." (PMID 36917086, 2023). "However, it remains unclear how tumor cell‐derived ANGPTL2 accelerates tumor progression in the context of tRCC." (PMID 37452654, 2023). "Thus, α5β1 integrin‐expressing cells, such as tumor and vascular cells, and PIR‐B‐expressing cells, such as dendritic cells, may compete for ANGPTL2 in the tumor microenvironment." (PMID 37452654, 2023). "Thus, changes in glycosylation of ANGPTL2 and/or its receptor in stromal versus tumor cells may also modulate ANGPTL2 activities in cancer pathology." (PMID 37452654, 2023). "We also indicate that ANGPTL2 promotes VEGF-A-dependent lymphangiogenesis via integrin α5β1, p38 MAP kinase (MAPK) and NF-κB signaling, indicating that ANGPTL2 may be worth targeting when applying tumor-associated lymphangiogenesis." (PMID 36917086, 2023). "Therefore, we may conclude that ANGPTL2 behave as a tumor promoter in GC just like in many other types of cancer." (PMID 32410376, 2020). "Moreover, higher ANGPTL2 serum levels correlate with more advanced TNM stage (large tumor, serosal invasion, venous invasion, lymph node, liver and peritoneal metastasis) demonstrating to be an independent predictor for tumor recurrence for CRC patients who underwent surgery." (PMID 29389861, 2018). "The predictive and prognostic values of ANGPTL2 in CRC are also supported in a recent study where authors showed that higher expression of ANGPTL2 in primary tumor tissues is related to aggressive phenotype of tumor cells and enhances resistance to antineoplastic drugs through apoptosis antagonism." (PMID 29389861, 2018). "In addition, ANGPTL2 expression being sensitive to hypoxia, epigenetic DNA methylation of ANGPTL2 promoter occurs in hypoxic tumour cells, leading to an increase in ANGPTL2 expression ultimately reinforcing the inflammatory response and the aggressive cancer cell phenotype." (PMID 29138671, 2017). "Finally, in the context of cancer, the tumours may also be the source of elevated ANGPTL2 systemic expression." (PMID 29138671, 2017). "Whether ANGPTL2 function differs in various tumor cell types remains to be determined." (PMID 25370833, 2015). "Taking theses findings together with our recent report that tumor cell-derived Angptl2 activates TGF-β1/Smad signaling, we speculate that Angptl2 contributes to the acceleration of tissue fibrosis through activation of the TGF-β1/Smad signaling cascade in various pathological settings." (PMID 24465594, 2014). "Collectively, these results suggest that ANGPTL2 suppresses IFNγ‐induced MHC‐I expression and intracellular MHC‐I antigen processing to attenuate antigen‐specific T‐cell activation and killing of tumor cells." (PMID 37452654, 2023). "Tumor stroma‐derived ANGPTL2 enhanced CD8+ T‐cell‐mediated anti‐tumor immune responses by activating dendritic cells via the PIR‐B receptor, leading to tumor suppression." (PMID 37452654, 2023). "Analysis of the Human Protein Atlas database revealed that ANGPTL2 and ANGPTL5 were highly expressed in HCC tumor tissues, while ANGPTL4 was decreased." (PMID 35692877, 2022). "In contrast, the DNA methylation levels of ANGPTL2, ANGPTL7, and ANGPTL8 were significantly positively correlated with tumor grade, and the DNA methylation levels of ANGPTL3, ANGPTL5, and ANGPTL7 were significantly negatively correlated with age." (PMID 35692877, 2022).
tumor (continued). "CAF-derived ANGPTL2, WWTR1, and PLOD2 promote tumor progression and cell invasion, and MYO10 regulates CAF rigidity." (PMID 33917869, 2021). "The location of tumor lesion also affected the expression level of ANGPTL1 (P = .0030), ANGPTL2 (P = .0014), ANGPTL3 (P = .0100), and ANGPTL4 (P = .0350) according to K‐W test." (PMID 32410376, 2020). "For instance, an autocrine signaling between ANGPTL2 and its receptor LILRB2 was able to induce early EMT and tumor progression in preneoplastic pancreatic ductal cells." (PMID 32410376, 2020). "In contrast, primary tumor growth rates for LM9, K7M2 and OS17 primary tumors were unaffected by downregulating ANGPTL2." (PMID 32082485, 2020). "Activation of metalloproteinases by ANGPTL2 via activation of p38 MAPK was also reported in cancer cells, contributing to increase tumour cell metastasis." (PMID 29138671, 2017). "Additional repressed genes were ANGPTL2, TGM2, IL-6, CSF1R, TNFSF12 as well as a key regulatory MAP kinase ERK1/2 (MAPK3), all known to stimulate chronic inflammatory signaling in the tumor microenvironment and to promote cancer metastasis." (PMID 24498382, 2014). "In addition, ANGPTL2 and SPP1 mainly distributed in the tumor microenvironment (TME) of CRC tissues." (PMID 37691929, 2023). "However, recently, we also showed that ANGPTL2–PIR-B signaling promotes DC activation and maturation and subsequent CD8+ T cell cross-priming, facilitating anti-tumor immune responses." (PMID 37736764, 2023). "Similar to our observations in patients, serum from mice injected with non-manipulated tumor cells (control shRNA) showed high levels of ANGPTL2." (PMID 32082485, 2020). "Moreover, we proved that an autocrine signaling between ANGPTL2 and its receptor LILRB2 was able to induce early EMT and the tumor progression of a model of pre-neoplastic pancreatic ductal cells." (PMID 29389861, 2018). "On the other hand, the tumour microenvironment activates transcription factors such as nuclear factor of activated T-cells (NFAT), c-Jun, and activated transcription factor 2 (ATF2), leading to an increased transcriptional expression of ANGPTL2." (PMID 29138671, 2017). "Our results provide intriguing clues that ANGPTL2/LILRB2 triggers several signaling pathways to support the stemness (self-renewal and differentiation) and migration ability for both normal stem cells and tumor cells." (PMID 26056041, 2015). "ANGPTL2 expression could discriminate patients who are more likely candidates to post-operative chemotherapy preventing tumor relapse, regardless of previous treatments." (PMID 29389861, 2018). "Therefore, tumor cell-derived ANGPTL2 may up-regulate ETS1-dependent activation of pro-angiogenic genes, promoting tumor angiogenesis." (PMID 25773070, 2015). "In this present study, we hypothesized that an autocrine signaling between ANGPTL2 and its receptor LILRB2 might be responsible for the early EMT and, in turn, the tumor progression in a model of multistep accumulation of genetic lesions in pancreatic ductal cells." (PMID 25360865, 2015).